ZNF568 (zinc finger protein 568)
Description:
Has transcriptional repression activity, partially through the recruitment of the corepressor TRIM28 but also has repression activity independently of this interaction. Essential during embryonic development, where it acts as a direct repressor of a placental-specific transcript of IGF2 in early development and regulates convergent extension movements required for axis elongation and tissue morphogenesis in all germ layers. Also important for normal morphogenesis of extraembryonic tissues including the yolk sac, extraembryonic mesoderm and placenta. May enhance proliferation or maintenance of neural stem cells.
Synonyms: PISA; DKFZp686B0797; ZFP568
Tractability: PROTAC: ubiquitination databases record sites on it.
Safety:
Unwanted effects reported when the protein is acted on. In parentheses: how it was acted on, where the effect was seen, and who reports it.
nausea and vomiting (source: ClinPGx)
Gene: Protein-coding gene on chromosome 19 (36,916,316 to 37,005,037, forward strand). Ensembl gene ENSG00000198453.
Subcellular location: Nucleus
Subcellular location (Human Protein Atlas): Nucleoplasm
Pathways (Reactome):
Gene expression (Transcription): Generic Transcription Pathway
Gene Ontology:
Molecular function: DNA-binding transcription factor activity, RNA polymerase II-specific; RNA polymerase II cis-regulatory region sequence-specific DNA binding; transcription cis-regulatory region binding; sequence-specific double-stranded DNA binding
Biological process: embryonic placenta morphogenesis; in utero embryonic development; negative regulation of DNA-templated transcription; negative regulation of transcription by RNA polymerase II; regulation of transcription by RNA polymerase II; regulation of DNA-templated transcription
Cellular component: nucleus
Genetic constraint (gnomAD): Loss-of-function variants: 13 observed, 19.99 expected, observed/expected ratio (o/e) 0.65, 90% interval 0.42 to 1.03. The upper end of that interval is the gene's LOEUF score, 1.03, which puts it in group 4 of 6, group 1 being the genes least tolerant of losing a copy. Missense variants: 639 observed, 805.84 expected, observed/expected ratio (o/e) 0.79, 90% interval 0.74 to 0.85. Synonymous variants: 213 observed, 255.18 expected, observed/expected ratio (o/e) 0.83, 90% interval 0.75 to 0.94.
Homologues: Orthologues: macaque ZNF568 (98% identical), rabbit ZNF568 (80% identical), guinea pig ZNF568 (77% identical). Paralogues in human: ZNF33B (48% identical), ZNF658 (47% identical), ZNF724 (46% identical), ZNF182 (46% identical), ZNF235 (46% identical), ZNF595 (46% identical), ZNF726 (46% identical), ZNF28 (46% identical), ZNF470 (46% identical), ZNF484 (46% identical), ZNF41 (45% identical), ZNF85 (45% identical), and 164 more.
Diseases named in the same sentence as ZNF568 in open-access papers:
ZNF568 is named in the same sentence as 14 diseases in open-access papers, as found by Europe PMC text mining. Sharing a sentence is not in itself a finding about the gene and the disease. The quoted sentences say what the papers report.
COVID-19 (1 paper, 2023). A disease caused by infection with severe acute respiratory syndrome coronavirus 2. "We developed a PRS model for severe COVID-19, which showed that variants detected in ZNF568, GPR173, PCDH15, and IGSF3 were associated with severe COVID-19." (PMID 37547597, 2023).
tumor (3 papers, 2018 to 2023). "Previous studies have revealed that C2H2 zinc finger proteins such as zinc finger E-box-binding homeobox 1 (ZEB1), ZNF475 and ZNF568 could enhance tumor cell glycolysis." (PMID 36977688, 2023).
cancer (2 papers, 2018 to 2020). A tumor composed of atypical neoplastic, often pleomorphic cells that invade other tissues. "Genotyping of the same 45 polymorphisms in 264 patients of the Italian CERP study, also treated with opioids for cancer pain, instead confirmed the association for two SNPs in ZNF568 and PDE3A genes." (PMID 31953506, 2020).
ZNF568 also shares sentences with these, for which no sentence is quoted: adenocarcinoma (1 paper); adenosquamous carcinoma (1); Alzheimer disease (1); asthma (1); colon cancer (1); colon polyps (1); colorectal cancer (1); colorectal tumor (1); rectal cancer (1); rectal tumor (1); squamous cell carcinoma (1).